METTL3 (methyltransferase 3, N6-adenosine-methyltransferase complex catalytic subunit)
Diseases named in the same sentence as METTL3 in open-access papers (continued):
Sharing a sentence is not in itself a finding about the gene and the disease.
Sepsis (39 papers, 2020 to 2025). Sepsis is defined as life-threatening organ dysfunction caused by a dysregulated host response to infection. "Subsequent Western blotting analysis revealed significantly diminished METTL3 expression in the lung tissues of these patients compared to healthy controls, suggesting a potential association between METTL3 dysregulation and sepsis pathogenesis." (PMID 41341492, 2025). "In sepsis-associated lung injury, p300-mediated H3K18la significantly upregulates METTL3 expression via enrichment in the promoter region of METTL3, driving ferroptosis in lung epithelial cells via m6A-dependent stabilization of ACSL4 mRNA." (PMID 40859309, 2025). "The examination provides a potential novel therapeutic strategy for sepsis-associated lung injury by blocking METTL3, targeting neutrophils and neutrophil extracellular traps with the corresponding inhibitors." (PMID 38988324, 2024). "N6-methyladenosine modification of Trim59 mRNA, mediated by METTL3, is implicated in the prevention of acute respiratory distress syndrome induced by sepsis." (PMID 38993561, 2024). "Research on the sepsis-associated characteristic gene METTL3 has been increasingly prevalent in recent years, with the goal of exploring potential epigenetic treatment targets for sepsis patients." (PMID 38112620, 2023). "In the sepsis-associated acute lung injury model, neutrophil extracellular traps induced ferroptosis in alveolar epithelial cells via activating the METTL3-YTHDF2-mediated m6A modification of GPX4." (PMID 38065948, 2023). "In the present study, we confirmed that NET‐activated METTL3 exacerbated ferroptosis via m6A‐IGF2BP2‐dependent mitochondrial metabolic reprogramming during the progression of sepsis‐associated lung injury." (PMID 37715457, 2023). "A recent study reported that METTL3-induced m6A modification on ferroptosis was involved in the pathogenesis of sepsis-associated acute lung injury." (PMID 38112620, 2023). "Our previous work confirmed that NETs induced METTL3‐mediated m6A modification of GPX4 via TLR9/MyD88/NF‐κB pathway in sepsis‐associated lung injury." (PMID 37715457, 2023). "Our in vivo CLP-induced sepsis and SI-ALI mouse model using METTL3 KO mice further demonstrated their critical roles in NETs-induced cell ferroptosis and protecting mice against sepsis-associated lung injury." (PMID 35637949, 2022). "Mechanistically, METTL3 inhibited endothelial injury in sepsis-induced ARDS through Trim59-associated NF-κB inactivation." (PMID 35693774, 2022). "Using a CLP-induced sepsis-associated ALI mouse model established with METTL3-/- versus WT mice, in addition to METTL3 knockout and overexpression in vitro, we elucidated and confirmed the critical role of ferroptosis in NETs-induced ALI." (PMID 35637949, 2022). "Compared with the sham group of mice, METTL3+/+ mice with sepsis-associated ALI showed massive infiltration of inflammatory cells in their lungs." (PMID 35637949, 2022). "To examine the role of METTL3 in sepsis-associated ALI in vivo, we used METTL3-/- versus WT mice for CLP-induced sepsis-associated ALI." (PMID 35637949, 2022). "Lower NETs levels with METTL3 knockout were accompanied by reduced ferroptosis in sepsis-associated ARDS mice, as indicated by reduced serum levels of ROS." (PMID 35637949, 2022). "We showed that METTL3 levels were decreased in sepsis-induced ARDS, and the knockdown of METTL3 exacerbated the damage to endothelial barrier integrity and the inflammatory response caused by sepsis in mice." (PMID 35693774, 2022). "Overall, these data suggest that knockdown of METTL3 aggravates damage to endothelial barrier integrity and the inflammatory response caused by sepsis." (PMID 35693774, 2022). "Taken together, these findings suggest that NETs-induced upregulation of METTL3 in alveolar epithelial cells and subsequent induction of ferroptosis play a novel role in sepsis-associated lung injury pathogenesis." (PMID 35637949, 2022).
Sepsis (continued). "Second, RNA-seq was used to detect the role of METTL3-mediated m6A modification in NETs-mediated ferroptosis in sepsis-associated lung injury." (PMID 35637949, 2022). "As expected, compared with sham control mice, METTL3+/+ mice with sepsis-associated ALI showed a significant increase in the wet-to-dry weight ratio and total cell number in BALF that was reduced by METTL3 knockout." (PMID 35637949, 2022). "Here, we showed that a decrease in m6A modifications was associated with downregulated METTL3 expression in sepsis." (PMID 35693774, 2022). "Mechanistically, METTL3 inhibits endothelial injury in sepsis-induced ARDS through Trim59-associated NF-κB inactivation." (PMID 35693774, 2022). "Studies indicate that enhanced formation of NETs in sepsis-associated ALI/ARDS activates METTL3-mediated m6A modification in alveolar epithelial cells, which regulates the stability of HIF-1α, thereby inducing mitochondrial metabolic reprogramming and ferroptosis, ultimately leading to lung injury." (PMID 41341492, 2025). "METTL3 promotes Slc7a11 mRNA degradation through m6A-dependent mechanisms, intensifying sepsis-induced cardiomyocyte ferroptosis—an iron-dependent, lipid per oxidation-mediated cell death strongly implicated in sepsis pathogenesis." (PMID 41341492, 2025). "The team conducted in vivo experiments using METTL3-knockdown murine models versus wild-type counterparts, and demonstrated that METTL3 deficiency exacerbated endothelial barrier disruption, amplified sepsis-induced inflammatory responses, and consequently aggravated pulmonary injury." (PMID 41341492, 2025). "Therefore, we concluded that METTL3 inhibits endothelial injury in sepsis-induced ARDS through Trim59-associated NF-κB inactivation." (PMID 35693774, 2022). "The reduced citH3-NE complex detected by IF analysis and reduced cfDNA in both the plasma and BALF detected by ELISA indicated that METTL3 knockout could significantly reduce NETs levels in sepsis-associated ALI mice." (PMID 35637949, 2022). "In CLP-induced sepsis-associated lung injury, lactate-driven H3K18 lactylation increases METTL3 expression, which in turn stabilizes ACSL4 mRNA via m6A methylation and YTHDC1 recognition, thereby promoting ferroptosis in alveolar epithelial cells." (PMID 41515964, 2025). "By modulating m6A RNA methylation in response to bacterial toxins, viral infections, sepsis, and radiation, METTL3 influences immune signaling, cell death, and tissue remodeling." (PMID 41515964, 2025). "H3K18la in alveolar epithelial cells during sepsis directly binds to the Methyltransferase-like 3 (METTL3) promoter region and promotes its transcription." (PMID 40563450, 2025). "For instance, histone protease-regulated METTL3 was shown to exacerbate sepsis-induced lung injury via m6A-mediated modification of ACSL4, promoting ferroptosis." (PMID 40625751, 2025). "In sepsis-associated ALI, NETs induce METTL3 expression, which in turn promotes ferroptosis in alveolar epithelial cells." (PMID 41515964, 2025). "N6-methyladenosine writer METTL3 can also accelerate the sepsis-induced myocardial injury by m6A modification of SLC7A11 via YTHDF2 pathway." (PMID 40356926, 2025). "METTL3-mediated m6A modification also facilitates TLR4 pathway activation to enhance neutrophil activation during sepsis." (PMID 40625751, 2025). "Methyltransferase-like 3 (METTL3)-mediated N6-methylation of adenosine in Trim59 mRNA protects against sepsis-induced ARDS by repressing NF-κB signaling and attenuating inflammatory responses." (PMID 41488672, 2025). "In general, macrophages are activated after the onset of sepsis resulting in the production of large amounts of LPS in the plasma and stimulating the upregulation of m6 A methyltransferase METTL3 expression." (PMID 36505499, 2022). "In septic cardiomyocytes, the expression or enrichment of m6A and METTL3 increased, suggesting the potential roles and regulation of m6A modification in sepsis-induced myocardial injury." (PMID 35840562, 2022).
Sepsis (continued). "Collectively, our in vitro results demonstrate the critical role of METTL3 in the regulation of vascular endothelial barrier function in sepsis-induced lung injury." (PMID 35693774, 2022). "To identify the role of METTL3 in sepsis-induced ARDS, we constructed METTL3-knockdown models in mice via intranasal administration of METTL3 siRNA or negative control (NC) siRNA." (PMID 35693774, 2022). "In conclusion, our findings support the role of METTL3 in sepsis-induced ALI pathogenesis through NETs-mediated m6A modification and subsequent ferroptosis of alveolar epithelial cells." (PMID 35637949, 2022). "We believe that this study provides critical clues to develop novel treatments for sepsis-induced ALI by targeting the PAD4/NETs/METTL3 pathway of alveolar epithelial cells." (PMID 35637949, 2022). "In conclusion, these findings revealed that m6A methyltransferase METTL3 participated in the myocardial injury induced by sepsis via the IGF2BP1/HDAC4 axis." (PMID 35840562, 2022). "Overall, macrophages are activated after the onset of sepsis resulting in the production of large amounts of LPS in the plasma and stimulating the upregulation of m6 A methyltransferase METTL3 expression." (PMID 36505499, 2022). "METTL3 regulated endothelial barrier dysfunction and inflammatory responses in sepsis-induced ARDS in vivo and in vitro." (PMID 35693774, 2022). "Our recent research showed that Mettl3 exacerbates I/R, sepsis, and vancomycin-induced AKI." (PMID 40765834, 2025). "Additionally, METTL3 has been proven to promote cell death, thereby exacerbating sepsis-induced acute lung injury." (PMID 41445732, 2025). "For example, in sepsis associated ALI, METTL3 may help maintain endothelial barrier integrity while exacerbating ferroptosis in epithelial cells." (PMID 41515964, 2025). "Furthermore, METTL3 was found to modulate endothelial function in sepsis-induced acute lung injury by inactivating NF-κB through Tripartite Motif Containing 59 (Trim59)-mediated mechanisms." (PMID 41341492, 2025). "In a mouse model of sepsis, NETs induced iron death in alveolar epithelial cells through activation of METTL3-m6A modification, a pathway that contributes to lung injury and systemic inflammation by promoting iron death via the NETs/p300/H3K27ac/METTL3-m6A/IGF2BP2-m6A/HIF-1α/GPX4/ROS pathway." (PMID 39108751, 2024). "In sepsis‐associated ALI, neutrophil extracellular trap production activates the ferroptosis signal, and the expression of METTL3 increases significantly to induce m6A modification of glutathione peroxidase 4, thereby causing ferroptosis in AECs and worsening lung injury." (PMID 38757482, 2024). "Using both in vitro and in vivo studies, our findings show enhanced NETs accumulation in sepsis-associated ALI patients and mice, as well as the closely related upregulation of ferroptosis, the induction of which depends on METTL3-induced m6A modification of GPX4." (PMID 35637949, 2022). "In conclusion, the findings illustrated a role of METTL3/IGF2BP1/m6A/HDAC4 axis on sepsis-induced myocardial injury, which might provide novel therapeutic strategy for septic myocardial injury." (PMID 35840562, 2022). "The degree of lung damage in sepsis-associated ALI mice with sepsis with or without METTL3 expression was then evaluated by detecting the lung injury score, lung wet-to-dry weight ratio and total cells in BALF." (PMID 35637949, 2022). "Identifying small molecule inhibitors targeting METTL3 may provide an innovative treatment strategy for sepsis-induced lung injury." (PMID 35637949, 2022). "Moreover, the m6A methyltransferase METTL3 expression increased with the increasing doses of LPS (0, 0.5, 1, 2, 5, 10 μg/mL) for 24 h for sepsis cellular model construction, including mRNA and protein." (PMID 35840562, 2022).
Sepsis (continued). "Taken together, these results reveal that m6A modification and METTL3 levels are decreased in sepsis-induced ARDS and that the occurrence of sepsis may be related to dysregulation of the m6A methyltransferase METTL3." (PMID 35693774, 2022). "We believe that blocking METTL3 can alleviate sepsis-induced ALI/ARDS." (PMID 35637949, 2022). "In the pathogenesis of sepsis associated acute lung injury, NETs can promote m6A modification and mitochondrial metabolic reprogramming of hypoxia inducible factor-1 α (HIF-1 α) induced by METTL3, leading to ferroptosis of alveolar epithelial cells and causing lung injury." (PMID 40356926, 2025). "CircN4bp1 mRNA may be upregulated in sepsis-induced acute respiratory distress syndrome macrophages with modification of METTL3-m6A, which further promotes M1 macrophage activation but inhibits M2 macrophage polarization through the CircN4bp1-miR-138–5p/EZH2 axis." (PMID 39108751, 2024). "Thus, we could derive the conclusion that METTL3 might act as an essential regulator in sepsis-induced myocardial injury, which is dependent on the m6A modification manner." (PMID 35840562, 2022). "However, it is unclear whether METTL3 promotes or inhibits inflammation in sepsis-induced lung injury." (PMID 35693774, 2022). "We observed substantial heterogeneity in the expression of demethylases (ALKBH5, FTO) and methyltransferase complex components (WTAP, METTL3, METTL14), suggesting their potential involvement in the epigenetic regulation of immune function during sepsis." (PMID 40625751, 2025). "First, METTL3 often acts as a key responder to injurious stimuli, including cigarette smoke, PM2.5, NETs, hypoxia, LPS and sepsis-related mediators." (PMID 41515964, 2025). "Previous studies have shown that in sepsis-related acute lung injury (ALI), lactate induces ACSL4-dependent ferroptosis in alveolar epithelial cells through METTL3-mediated m6A modification via the H3K18la/METTL3/ACSL4 axis." (PMID 41461917, 2025). "By contrast, in sepsis-induced ALI, METTL3 appears protective: activation of the Trim59-NF-κB axis helps curb inflammation and maintain endothelial barrier integrity." (PMID 41515964, 2025). "Recent studies have identified METTL3 as a central epigenetic regulator in both viral and bacterial lung infections, including pneumonia, acute respiratory distress syndrome (ARDS), and sepsis-related inflammation." (PMID 41515964, 2025). "In the same way, METTL3 can regulate sepsis-induced myocardial injury through an IGF2BP1/HDAC4-dependent mechanism, and knockdown of METTL3 greatly inhibits myocardial cell damage." (PMID 39234245, 2024). "For example, a recent study revealed that METTL3 mediates the m6A methylation of SIRT1 mRNA, which suppresses SIRT1 protein expression and autophagic flux and eventually results in sepsis-induced acute lung injury." (PMID 38112620, 2023). "The in vivo model of CLP-induced sepsis and the murine model of SA-AKI using METTL3 KO mice further demonstrate the critical role of METTL3-mediated m6A modification in NET-induced ferroptosis and protection of mice from SA-AKI." (PMID 36505499, 2022). "VEGF has also been reported to be increased in response to septic inflammation, which provides a reasonable explanation for the regulation of METTL3, METTL14, and IGF2BP3 in sepsis." (PMID 34869371, 2021). "Knocking out METTL3 markedly reduced circN4BP1 expression, regulating downstream EZH2 expression, further influencing macrophage polarization, and ameliorating the inflammatory response induced by sepsis-induced ARDS." (PMID 39234245, 2024). "They activate TLR9/MyD88/NF-kβ pathway, up-regulate METTL3 expression, and promote m6A modification of GPX4, resulting in reduced GPX4 expression and triggering alveolar epithelial cell ferroptosis in the pathogenesis of sepsis-induced acute lung injury." (PMID 38988324, 2024).
Sepsis (continued). "Mechanically, METTL3 catalyzed m6A modification of HDAC4 mRNA, and IGF2BP1 identified the m6A site on HDAC4 mRNA and strengthened its stability, which consequently stimulates the inflammatory damage of cardiomyocytes induced by sepsis." (PMID 38112620, 2023). "Likewise, YTHDF2 recognizes METTL3-mediated m6A modification of SLC7A11 mRNA and promotes the degradation of SLC7A11 mRNA, ultimately leading to ferroptosis in sepsis-induced myocardial injury." (PMID 38112620, 2023). "Therefore, METTL3 and METTL14 worked in a protective role to maintain microvascular circulation and myocardial function during sepsis." (PMID 34869371, 2021). "Functionally, YTHDF1 recognized and stabilized METTL3-mediated m6A-modified tripartite motif-containing (Trim59) mRNA to protect the vascular endothelium against barrier dysfunction and inflammatory responses, which inhibits the evolution of ARDS during sepsis." (PMID 38112620, 2023). "Therefore, it is plausible that downregulation of METTL3 and WTAP may modulate aortic damage during sepsis." (PMID 34507301, 2021). "Using qRT-PCR, we detected that the expression of METTL3 and WTAP in the aorta was significantly downregulated during sepsis, while that of YTHDF 1, YTHDF 3, METTL14, and FTO did not change significantly." (PMID 34507301, 2021).